SERTAD4BP (SERTA domain containing 4B, pseudogene)
Synonyms: formerly LINC00643
Gene: Transcribed unitary pseudogene on chromosome 14 (62,117,346 to 62,128,397, forward strand). Ensembl gene ENSG00000186369.
Diseases named in the same sentence as SERTAD4BP in open-access papers:
SERTAD4BP is named in the same sentence as 2 diseases in open-access papers, as found by Europe PMC text mining. Sharing a sentence is not in itself a finding about the gene and the disease.
SERTAD4BP shares sentences with these, for which no sentence is quoted: cancer (1 paper); tumor (1).